IL1B (interleukin 1 beta)
Diseases named in the same sentence as IL1B in open-access papers (continued):
Sharing a sentence is not in itself a finding about the gene and the disease.
gastric cancer (continued). "MCP-1 expression was correlated with IL-1β expression in gastric cancer tissues." (PMID 24993819, 2014). "Many studies have also demonstrated that p38 participates in IL-1β signaling cascades in a set of cell types, especially in mouse embryonic fibroblast (MEF) cells and macrophages cells; however, very little is known about the function of IL-1β-activated p38 in gastric cancer." (PMID 24479681, 2014). "Our results demonstrate that Wnt5a induces MCP-1 production in gastric cancer, which is mediated by IL-1β, suggesting that Wnt5a is involved in macrophage recruitment, and IL-1Ra may be used to inhibit macrophage recruitment in gastric cancer." (PMID 24993819, 2014). "The present study reveals a close link between MCP-1 and IL-1β in gastric cancer." (PMID 24993819, 2014). "To determine whether gastric cancer cells secreted IL-1α or IL-1β to activate fibroblasts, we measured the concentrations of IL-1α and IL-1β in cancer cell–conditioned media." (PMID 23593346, 2013). "In addition, an animal model has demonstrated that elevated levels of IL-1β are sufficient to induce dysplasia and gastric cancer." (PMID 24892619, 2013). "These inflammatory cytokines may play a key role during carcinogenesis and tumor formation as the transgenic overexpression of IL1β in gastric mucosa was sufficient to induce gastric cancer in mice." (PMID 22735354, 2012). "The hypothesis has been proposed that polymorphisms in genes involved in inflammatory response, such as IL-1A, IL-1B, IL-6, IL-8, may help explain why only a subset of individuals infected with H. pylori develops gastric cancer." (PMID 21071884, 2011). "The two promoter variants of IL1B, −511C>T and −31T>C SNPs, have been repeatedly associated with multiple clinical conditions such as cardiovascular disease and gastric cancer as well as with clinically observed differences in the levels of IL1β protein in vivo." (PMID 19043479, 2008). "Therefore, we induce that gene-controlled high production of IL-1β are likely to play some role in the occurrence of cachexia from patients with advanced gastric cancer." (PMID 17359523, 2007). "Therefore, downregulating the production of IL-1β mediated by Helicobacter pylori may be a way to prevent gastric cancer." (PMID 38182564, 2024). "The overexpression of IL-1β was recently identified as a signature of the intestinal metaplasia stage in the fundus of H. pylori-infected patients, an advanced stage that could progress toward gastric cancer." (PMID 36838318, 2023). "Additionally, Helicobacter pylori infection enhances NLRP3 expression and subsequent inflammasome activation and IL-1β release in macrophages, which could enhance the tumorigenesis of gastric cancer." (PMID 35990696, 2022). "Similarly, IL-1β-mediated inflammatory signaling accounted for the promoter hypermethylation and gene silencing of E-cadherin, which is important for impeding cell migration and metastasis, based on a mouse model of gastric cancer." (PMID 35757000, 2022). "Moreover, increased IL-1β levels in the stomach epithelium could contribute to the development of gastric cancer by increasing the number of myeloid-derived suppressor cells." (PMID 35990696, 2022). "Thus, by selectively upregulating IL-18 but suppressing IL-1β, H. pylori LPS not only inhibits the immune inflammatory response but also promotes gastric cancer cells’ escape from immune surveillance, which facilitates gastric cancer initiation and progression." (PMID 33217986, 2020). "The histological type of gastric cancer may be also dependent on IL-1β." (PMID 30123433, 2018). "Interestingly a meta-analysis of the role of IL-1β and it's antagonist gene polymorphisms in gastric cancer risk showed an association in Caucasians, but not in Asian populations." (PMID 30409143, 2018).
gastric cancer (continued). "Host genetic polymorphisms of several cytokine genes (e.g., IL-1B-511*T, IL-1-RN*2, IL-10-1082/-819/-592, TNF-A-308*A, and IL-8-251*A), innate immune response gene (TLR4+896*G), HLA (DQA1*03:01, DQA1*04:01, and DQB1*05:01:01) are involved in all stages of the neoplastic process in gastric carcinoma." (PMID 28384207, 2017). "However, as this meta‐analysis covered overall various cancer types, the association of IL‐1B 31 polymorphism and gastric cancer risk were not analysed deeply enough." (PMID 26805397, 2016). "However, while much of the current literature has focused on the pro-tumorigenic effects of IL-1β, particularly in gastric cancer, IL-1α, which was preferentially expressed in gp130757FF xIL-1RT1−/− cardiac lesions at the expense of IL-1β, has been poorly studied in comparison." (PMID 25528766, 2015). "Moreover, IL-1β promoted migration and invasion of the gastric cancer cells may be mediated by matrix metalloproteinase-9 (MMP9) as other searchers reported." (PMID 24223129, 2013). "IL-1β levels have been associated with gastric cancer, and because the SEPS1 polymorphism affects the levels of IL-1β, the SEPS1 polymorphism may be an important genetic factor for the development of gastric cancer." (PMID 19144102, 2009). "However, a significantly increased frequency of IL-1B+3954 T allele was noted in patients with cachexia from locally advanced gastric cancer, which has not been reported previously." (PMID 17359523, 2007). "In our study, we observed that TFF1 expression was downregulated in gastric cancer-derived KATO III cells upon exposure to IFNγ alone, whereas in primary human gastric mucosoids, its repression required a combination of TNF-α, IL-1β, and IFNγ." (PMID 41573568, 2025). "AGS gastric cancer cells have diminished levels of TNF-α, IL-1β, and interleukin-8 (IL-8) as a result of this activity, which also includes the production of the genes for cytotoxin-associated gene A (CagA) and vacuolating cytotoxin A (Vac A)." (PMID 40238859, 2025). "Tα1 increased the percentage of CD4+CD25+Foxp3+ (suppressive antitumor-specific Tregs), Tregs, IL-1β, TNF-α, and IL-6 in patients with gastric carcinoma." (PMID 40599771, 2025). "Collectively, these results demonstrated that Triptolide suppresses the IL-1β-induced IL-8 expression in gastric cancer AGS cells and further inhibited the IL-1β-induced cancer cell proliferation." (PMID 39950099, 2024). "Although NLRP6 was reported to serve as a tumor suppressor in colorectal cancer, hepatocellular carcinoma, and gastric cancer, it was reported to restore immune evasion and radio-resistance in glioma through ASC/caspase-1/IL-1β axis." (PMID 38678251, 2024). "Our findings demonstrated that IL-1β increased IL-8 expression by upregulating reactive oxygen species (ROS), ERK, AP-1, and NF-κB signaling pathways in gastric cancer cells, and that all these signaling pathways can be inhibited by Triptolide treatment." (PMID 39950099, 2024). "Elevated levels of inflammatory markers, including interleukin-1 beta (IL-1β), C-reactive protein (CRP), and tumor necrosis factor-alpha (TNF-β), have been identified in CP and gastric cancer." (PMID 37568790, 2023). "To further examine the anti-apoptosis mechanism of the volatile oil of R. rubescens in gastric cancer cells, we performed western blotting to detect the four core targets, TNF, IL1B, MPP9 and PTGS2." (PMID 36200190, 2022). "Our previous study demonstrated the anti-metastatic function of piperine by blocking IL-1β-stimulated IL-6 via the downregulation of the p38 and STAT3 activation in gastric cancer TMK-1 cells." (PMID 35326180, 2022). "The high expression of NLRP3 in gastric cancer promotes the activation of NLRP3 inflammasome and the secretion of interleukin-1β (IL-1β) in macrophages." (PMID 36541912, 2022). "Gastric cancer (GC)‐derived TNF‐α and IL‐1β enhanced the motility of CAFs to induce GC metastases." (PMID 34459125, 2021).
gastric cancer (continued). "Herein, we further showed that famotidine stimulation in gastric cancer cells of BGC823 and AGS significantly promoted cell pyroptosis by inducing NLRP3 activation, leading to caspase-1 activation, IL-1β and IL-18 release." (PMID 34686215, 2021). "When melatonin was used, the IL-1β/NF-κB/MMP-2/MMP-9 genes' expression and also invasion of gastric cancer cells reduced significantly." (PMID 34054953, 2021). "It was indeed demonstrated that the inflammatory cytokines IL-1β and IL-8, but TGFβ also induced EGFR trans-activation in gastric cancer cells, particularly via soluble amphiregulin and HB-EGF." (PMID 32698506, 2020). "E. The expression of pro-inflammatory factors (IL-1β, IL-6, IL-8, OSM, and TNFα) in gastric cancer cell-derived exosomes-treated neutrophils was determined by qRT-PCR." (PMID 30292233, 2018). "Investigations of the molecular mechanism responsible for NF-κB activation in infected gastric cancer cell lines revealed the involvement of the IκB kinases (IKK) complex downstream of TRAF6-TAK1 signaling, similar to IL-1β-induced NF-κB regulation." (PMID 28350359, 2017). "IFN-γ and IL-10 were significantly higher in both intestinal and diffuse gastric cancer, whereas IL-1β and IL-6 were higher and TGF-β lower only in intestinal gastric cancer; MCP-1 was lower only in diffuse gastric cancer." (PMID 28558708, 2017). "Levels of IL-1β, IL-6, IFN-γ, and IL-10 were significantly higher and that of MCP-1 was lower in gastric cancer patients compared with controls." (PMID 28558708, 2017). "The reconstitution of TFF1 expression in gastric cancer cells suppressed H. pylori mediated NF-κB activation and expression of cytokine genes (TNF, IL-1β, CCL5, and IL-4 receptor)." (PMID 28350359, 2017). "Wnt5a was overexpressed in gastric cancer tissues, and correlated with monocyte chemotactic protein 1 (MCP-1) and interleukin 1β (IL-1β), respectively." (PMID 24993819, 2014). "Moreover, this study has shown that rIL-1Ra can suppress Wnt5a-induced MCP-1 upregulation and macrophage chemotaxis, suggesting IL-1β blocking may be used to inhibit the aberrant macrophage infiltration, and suppress the development of chronic gastric inflammation and gastric cancer." (PMID 24993819, 2014). "In this study, we found that M.hy triggered IL-1β secretion in a NLRP3 inflammasome-dependent manner, and the resulting IL-1β induced migration and invasion of gastric cancer cells." (PMID 24223129, 2013). "Previous studies showed that lentinan elicited peritoneal macrophages with increased secretion of IL-12 in vitro and reduced IL-10 in vivo and enhanced the production of IL-1β and TNF-α in peripheral monocytes from the patients with gastric carcinoma." (PMID 24223225, 2013). "IL1B promotes the shedding of heparin-binding EGF-like growth factor (HB-EGF), an EGFR ligand, in gastric cancer cells." (PMID 23115635, 2012). "In the advanced disease study, the proportion of patients with detectable IL1β was significantly higher in gastro-oesophageal junction cancers than in other sites (p = 0.006) and IL12 was detected more frequently in gastric cancers, although this was borderline significant (p = 0.051)." (PMID 41249451, 2026). "In addition, in gastric cancer (GC) through regulation of miR‐223‐3p/NLRP3 axis to induction of NLRP3 inflammasome activation and upregulation of IL‐1β secretion which drives epithelial cell proliferation and tumorigenesis." (PMID 40671401, 2025). "This study reveals distinct molecular profiles in gastric cancer immunotherapy responders (IL1B/IFN-γ-driven immunity) versus non-responders (galectin-3/complement-mediated suppression)." (PMID 40723289, 2025). "In human gastric cancer cells, CORM-2 also abrogates IL-1β-induced ROS production." (PMID 38263152, 2024). "To summarize, Triptolide treatment inhibited the IL-1β-induced IL-8 expression by suppressing the ERK/AP-1/NF-κB signaling, which decreased ROS generation and tumor proliferation and angiogenesis of human gastric cancer AGS cells." (PMID 39950099, 2024).
gastric cancer (continued). "Loss of AQP3 might lead to reduced expression of inflammatory factors like IL-6 and TNF-α, and AQP3 inhibition could decrease the production of IL-6, IL-1β, and TNF-α, impairing intestinal bacteria clearance and contributing to gastric cancer progression." (PMID 39060229, 2024). "This is consistent with the results of previous studies that added GLP that 400 mg/kg GLP reduced serum levels of IL-1β and IL-6 in diabetic rats, and 800 mg/kg GLP reduced serum IL-6 and TNF-α levels and increased serum IL-2, IL-4, and IL-10 levels in rats with gastric cancer." (PMID 39457856, 2024). "Their findings suggest that Triptolide might inhibit IL-1β expression directly, which in turn inhibits IL-8 expression in AGS gastric cancer cells." (PMID 39950099, 2024). "Besides cell death, GSDME activation leads to the production and secretion of IL-1α and IL-1β from macrophages, IL-1β from neutrophils, HMGB1 from intraepithelial cells, and IL-18 from gastric cancer cell lines." (PMID 37664463, 2023). "Our findings indicate that the volatile oil of R. rubescens may promote the apoptosis of gastric cancer cells by inhibiting the expression of TNF, IL1B, MPP9, and PTGS2." (PMID 36200190, 2022). "The pro-inflammatory cytokines IL-1β, TNF, and IL-6 can induce the transition of EMT in head and neck cancers and anti-inflammatory cytokine IL-10 can lead to tumor cell proliferation through an induction of STAT3 activation in gastric cancer cells." (PMID 35283421, 2022). "TNF, IL1B, and MMP9 play important roles in the occurrence and development of gastric cancer." (PMID 36200190, 2022). "Moreover, Mycoplasma hyorhinis, which was detected in 56% of gastric cancer, was also found to be able to active NLRP3 inflammasome and induce IL-1β secretion, thus promote gastric cancer cell migration and invasion." (PMID 36619871, 2022). "We found that the volatile components of R. rubescens could inhibit the activity of gastric cancer cells, possibly by regulating the levels of TNF, IL1B, MPP9 and PTGS2." (PMID 36200190, 2022). "In addition to the potential role of neutrophils in gastric-cancer development, a recent study has also shown that H. pylori T4SS induced production of IL-1β in human neutrophils in a NLRP3 inflammasome-dependent manner." (PMID 32582201, 2020). "The presence of IL-1β-511T, IL-1RN*2/*2, TNF-α-308A, and IL-10 (haplotype ATA/ATA) was connected to a higher risk of noncardia gastric cancer with H. pylori infection." (PMID 30123433, 2018). "Also, treatment of gastric cancer cell lines (TMK-1, MKN-74, and MKN-7) with IL-1β has been reported to have induced the methylation of tumor-suppressor gene CDH1, based on a conventional methylation-specific PCR." (PMID 26823082, 2016). "In SGC7901 gastric cancer cells, TGR5 ligand 23(S)-mCDCA suppresses gene expression of IP-10, interleukin (IL)-6, IL-1β, and MCP-1 mediated by NF-κB while GPBARA treatment suppresses gene expression of IP-10, IL-1β, and MCP-1 mediated by NF-κB." (PMID 26696888, 2015). "In gastric cancer cells, Wnt5a induced MCP-1 expression, which was mediated by IL-1β." (PMID 24993819, 2014). "H/K-ATPase-IL-1β transgenic mice (C57BL/6 background) exhibited spontaneous gastric inflammation and slow progression (over 1.5 years) to gastric atrophy, metaplasia and gastric cancer." (PMID 24216700, 2013). "Our study found that M.hy induced IL-1β promoted migration and invasion of the gastric cancer cells, while M.hy induced IL-18 did not contribute to the migration and invasion of gastric cancer cells, which was different from other reports." (PMID 24223129, 2013). "Similarly, we also observed that in gastric cancer cell line AGS, IL1B induced Smad 7, inhibits the phosphorylation of Smad 3 and subsequently interferes with gastrin expression." (PMID 21445336, 2011). "Host genetic factors that affect IL-1β may determine why some individuals infected with H. pylori develop gastric cancer, while others do not." (PMID 40141175, 2025).
gastric cancer (continued). "In addition to the anti-inflammatory effects of PF treatments by the inhibition of IL-1β, IL-6, and TNF-α on LPS-treated Raw264.7 cells, the current study shows that PF treatments decreased tumor volume and induced cytotoxicity in gastric cancer cells in vivo and in vitro." (PMID 38140352, 2023). "MiR-100-3p has been shown to control the proliferation and the apoptosis of human gastric cancer cells via binding to bone morphogenic protein type 2 receptor (BMPR2), and it may be involved in producing interleukin (IL)-8 and IL-1β in mesangial cells." (PMID 34046405, 2021). "In addition, IL-1B and TNF-α levels have been shown to increase in H. pylori-infected Pol β mutant mouse gastric mucosa, which may stimulate gastric dysplasia and gastric cancer development." (PMID 31216714, 2019). "Importantly, it is IL-1β but not IL-18 produced from macrophages challenged with M.hy promoted gastric cancer cell migration and invasion." (PMID 24223129, 2013). "In this meta-analysis IL1B −511T allele and IL1RN*2 variable number of tandem repeats (VNTR) are significantly associated with an increased risk of developing gastric carcinoma and even more significantly with non-cardia gastric carcinoma or with intestinal type gastric carcinoma." (PMID 23995914, 2013). "Likewise, studies conducted in a lung metastasis model of gastric cancer have shown that melatonin reduced the number and size of the lung metastatic nodules and reversed the induction of several EMT markers, such as vimentin, fibronectin and Snail, by interleukin 1 beta (IL-1β)." (PMID 38473317, 2024). "IL-1α and IL-1β mRNA expression is upregulated in antral tumors of gp130757FF mice, consistent with the view that IL-1RT1 ligands may contribute to the development of gastric antral tumors in this STAT3-dependent model, and may serve as novel therapeutic targets for gastric cancer." (PMID 25528766, 2015). "Further results showed that famotidine triggered cell pyroptosis in gastric cancer cells by activation of NLPR3 inflammasomes including ASC, Caspase-1 and NLRP, leading to enhanced IL-18, not IL-1β, mature and secretion." (PMID 34686215, 2021). "Similar to our results, a gastric cancer study found that neither G-CSF, GM-CSF, TGF-β, M-CSF, IL-1β, IL17A, IL-6, TNFα, IL10, IFNγ and IL22 were able to induce MC degranulation, while only adrenomedullin did." (PMID 32722549, 2020).